IFNG (interferon gamma)
Diseases named in the same sentence as IFNG in open-access papers (continued):
Sharing a sentence is not in itself a finding about the gene and the disease.
infection (continued). "The gene expression of TNFα, IFNγ and IL-10 within ‘ATL-like’ cells was higher in patients with non-malignant infection compared to ATL (p = 0.048, p = 0.031 and = 0.056 respectively) in keeping with relative frequencies of cytokine secreting cells by intracellular cytokine staining." (PMID 29444188, 2018). "The contribution of IFNγ in H1N1 influenza infection remains controversial, with some data suggesting a role for IFNγ in CD8+ T cell homeostasis, while others indicate that IFNγ signaling blockade does not alter infection resolution." (PMID 30410021, 2018). "In comparison, although mice that received HSV-2 + Cc-Griffithsin had elevated IFNγ in the vaginal tract at 24 hours post-infection, this was not significantly greater than HSV-2 alone or HSV-2 + Cc-Control, and about a third the amount of IFNγ that the HSV-2 + Cc-A1AT mice produced." (PMID 29434285, 2018). "Beyond a simple lack of correlation between IFNγ levels and protection in MTB infection, there is even evidence that IFNγ production has to be tightly controlled to prevent damage to the host, particularly the lung tissue, during infection." (PMID 29312343, 2017). "Interestingly, VSVΔ51-GFP (multiplicity of infection (MOI) 0.1) and IFNγ (1000 U/mL) were not effective when used as a single agent, but both agents synergized with LCL161 to significantly reduce viability in Kym-1 cells." (PMID 27966453, 2017). "However, the absolute number of IFNγ+ cNK cells per organ did not increase significantly after RH and ME49 infection." (PMID 27721814, 2016). "Upon infection, CD8+, but not CD4+ cells, increased rapidly in proportion and IFNγ production." (PMID 28119902, 2016). "Whether or not the low numbers of IFNγ+ and CD107a+ cNK cells responding to RH and ME49 infection are sufficient to control infection is not clear." (PMID 27721814, 2016). "It was also demonstrated that CD49b+ CD3+ natural killer T (NKT) cells increased in the liver after a primary infection with P. yoelii non-lethal strain (17XNL), and that CD1d-restricted NKT cells, which secrete IFNγ, are critical to reduce liver-stage burden in a secondary infection." (PMID 27446022, 2016). "Interestingly, similar to IFNγ+ cNK cells, RH infection resulted in a significant decrease in CD107a+ cNK cell numbers, while ME49 induced less of a decrease and cps1-1 infection did not alter cNK cytotoxic responses in the spleen." (PMID 27721814, 2016). "Of note, IFNγ transcript levels and TH1 frequencies were also elevated in WT chimeras; however, these cells did not display CD121a expression and were resistant to the infection." (PMID 25761673, 2015). "Conversely, 15 days after treatment of blood stage infection with chloroquine, splenocytes showed spontaneous in vitro expression of TNFα, IL2, IL6, IL10, and IL12, but not IFNγ, and stimulation with P. falciparum pRBC blocked the expression of all these cytokines." (PMID 25890318, 2015). "Furthermore, the lack of the P2X7R during MP287/03 Mbv infection did not affect the low production of IL-1β by lung infiltrating cells, but it restored the CD4+ and CD8+ T cell responses with the secretion of more IFNγ and less IL-10." (PMID 24991816, 2014). "Moreover, they help to clear infected cells early after infection also in the absence of CD8-positive T-cells by antibody-independent, cytotoxic mechanisms or interferon-gamma secretion." (PMID 24376753, 2013). "Throughout infection IDO activity remained at basal levels in lungs of X31-infected IFNγR1-KO mice, relative to basal IDO activity in lungs from uninfected mice (not shown), indicating that IFNγ induced IDO in infected lungs." (PMID 23785507, 2013). "In contrast to ex-vivo stimulation of human tonsil cells and in contrast to previous studies using GAS-M89, expression of functional SMEZ during intramuscular infection of HLA-DQ8 transgenic mice did not increase local tissue levels of TNFα, IL-10, IL-17 or IFNγ." (PMID 23049698, 2012).
infection (continued). "Looking next at STAT1 serine phosphorylation, we found that infection with any of the Toxoplasma strains that we tested induced the serine phosphorylation of STAT1 slightly, but none of these strains strongly inhibited IFNγ induced serine phosphorylation of STAT1." (PMID 23240025, 2012). "Infection with Tn:Rv0431 resulted in greater expression of transcripts for IL-12p40, IL-6, Delta4, CD40, GM-CSF, RANTES, TNFα and MCP-1, but not GITRL or iNOS, than WT Mtb, both with (not shown) or without IFNγ costimulation." (PMID 21170273, 2010). "Note the smaller scales for the cytokines in panels A and B.)Levels tended to normalize to baseline values within 3–4 weeks of infection in all animals, with IL2, IL4, IL12p40, IFNγ, and CCL3 increasing again after 6 weeks of SHIV-RT infection of the naïve animals (not statistically significant)." (PMID 20011586, 2009). "The low levels of S-specific IFNγ-producing PBMC levels observed in volunteers in phase IIb on day 0 indicate that those volunteers were predominantly SARS-CoV-2 naïve, and that it was vaccination and not infection that led to the increase in anti-N IgG quantities over time observed in that phase." (PMID 38276672, 2024). "The lack of IFNγ expression within the brain and absence of CCR1 on microglia may prevent their activation, thus contributing to the shift in viral tropism to resident microglia which consequently became the main target of infection." (PMID 37037810, 2023). "We also noted that ∆3678-vaccination in mice with prior SARS-CoV-2 infection had stronger CD8+IFNγ+ T cell response in the lung, stronger CD4+IFNγ+ T cells and CD8+IFNγ+ T cells in the spleen, and stronger SARS-CoV-2- specific IgG2c responses in the sera compared to those without prior infection." (PMID 37863935, 2023). "We next quantitated IFNγ-producing T cells in the lungs and found that both endogenous and P25TCR-Tg IFNγ-producing T cells were more abundant in mice infected with 4334 than H37Rv at day 14 post infection, though the difference was not statistically significant." (PMID 35695454, 2022). "In addition to the correlation involving IFNγ, a moderate, negative, and significant correlation was observed between the BMP2 level and the number of myenteric plexus neuron cells but only during the acute phase of the experimental infection." (PMID 33561140, 2021). "Furthermore, while mice lacking either MyD88 or IL12p40 succumb rapidly to infection, mice that lack Myd88 specifically in DCs or macrophage lineages do not, indicating that there are other factors and cytokines that regulate IL12 and IFNγ secretion." (PMID 33178630, 2020). "Lastly, it might be that adoptive transfer of an isolated T cell subset such as CD8+ Tc17 cells is not enough to protect the mice from infection and that other T cell subsets such as CD4+ Th17 cells or IFNγ-producing Th1 and Tc1 cells are required for protection." (PMID 32582196, 2020). "However, IFNγ-expression is strongly dependent on gGT activity, suggesting that CD4+ T cells might not be the major source of IFNγ during infection." (PMID 29057967, 2017). "Since IFNγ given 48 hours following infection did not protect IFNAR-/- mice against EBOV GP/rVSV, in these studies we assessed the protection IFNγ conferred against MA-EBOV when administered 24 hours prior to, at the time of infection, 6 or 24 hours following infection." (PMID 26562011, 2015). "We found that cytokines typically of effector T cell origin (e.g. IFNγ, IL-10, and TNF) were not significantly altered in WT and KO mice, although there was a general trend toward higher cytokine levels in IL-21R KO mice late after infection (i.e. day 14 p.i.)." (PMID 25849970, 2015). "Interestingly, while Th1 responses in Irf5-/- mice were severely impaired 4 weeks after infection, expression of IRF-5 was not required during the first 2 weeks of infection, since the frequency of IFNγ-producing CD4+ T-cells in Irf5-/- mice was comparable to WT mice." (PMID 21253574, 2011).
infection (continued). "However, during infection by a type I virulent T. gondii strain, few vacuoles accumulate IRG proteins in large amounts or disrupt, and parasite replication in cells is not inhibited by IFNγ." (PMID 21203588, 2010).
cancer (3,533 papers, 1991 to 2026). A tumor composed of atypical neoplastic, often pleomorphic cells that invade other tissues. "Extending these observations, we found that AR activity is negatively associated with IFNγ pathway activity at the pan-cancer level." (PMID 41486951, 2026). "Specifically, our GSEA analysis revealed a significant association between UCK2 expression and IFNγ in four different types of cancer." (PMID 39931080, 2025). "The main pathways significantly associated with IFI30 in pan-cancer are “Interferon gamma response, Interferon alpha response”, “inflammatory response, allograft rejection”, and “complement pathway activation”." (PMID 39925804, 2025). "This is particularly important as others have recently shown that elevated ACSL4 modulates cancer cell membrane lipid composition in vivo and makes them susceptible to T cell-derived IFNγ induced ferroptosis." (PMID 40382332, 2025). "Communication pathways strongly associated with high cancer interferon gamma response phenotype activation were found using Lasso regression." (PMID 40032842, 2025). "Overall, cytokines associated with effector lymphocyte cytotoxicity response (IFNg, perforin, granzyme A, granzyme B, and granulysin), cell death (FasL and TNFa), and IL-17A showed strong positive correlation with cancer cell killing (p = 0.025 to p < 0.0001)." (PMID 40589567, 2025). "CXCL10 is a potent chemoattractant produced in response to IFNγ stimulation that subsequently promotes T-cell trafficking to tumors and is associated with improved survival in multiple cancer types." (PMID 41463176, 2025). "Cytotoxic T (CD8+) and T‐helper 1 (Th1) cells, through the secretion of cytokines like interferon‐gamma (IFN‐γ), are associated with positive prognostic outcomes in many cancers, including HNSCC." (PMID 40127161, 2025). "SFV/IFNγ inhibited cancer-associated pathways (angiogenesis, glycolysis and extracellular matrix (ECM) remodelling) and enhanced cytotoxic lymphocyte (CTL) chemoattractants (CXCL9 and CXCL10)." (PMID 40547518, 2025). "High local concentrations of IFNγ and tumor necrosis factor α (TNFα), secreted by tumor-associated macrophages, prompt cancer cells to express programmed death ligand 1 (PD-L1)." (PMID 39744013, 2024). "Previous research has shown that elevated levels of IFNγ are associated with favourable clinical outcomes in cancer patients undergoing anti-PD1/PDL1 treatment and are closely linked to PDL1 expression." (PMID 38566204, 2024). "Our genome-wide CRISPR screens suggest that ‘Jak-STAT signaling pathway’ is highly associated with anti-PD1 responsiveness, and altered IFNγ signaling pathway has been implicated as a molecular mechanism underlying resistance to cancer immunotherapy." (PMID 39095793, 2024). "B7-H3–high tumors in most cancer types displayed positive enrichment of Hallmark inflammatory response gene sets, Hallmark IFNγ response gene sets, Hallmark TNFα response gene sets, and Hallmark IFNα response gene sets." (PMID 38709075, 2024). "The upregulation of SHC1 activated immune-associated and cancer-related pathways, such as epithelial-mesenchymal transition, interferon-gamma response, inflammatory response, and the IL6/JAK/STAT3 pathway." (PMID 38763954, 2024). "PSMB8, PSMB9 and PSMB10 are part of the immunoproteasome complex, which is activated in response to interferon gamma signaling, and has been previously associated to cancer cell survival and progression." (PMID 38519482, 2024). "IFNγ is a pro-inflammatory cytokine and its production is a typical hallmark of activated Vγ9Vδ2 T cells associated with their effector functions in cancer." (PMID 37539052, 2023). "IFNG+ status was associated with exhaustion or resident memory-characteristics whereas IFNG– status associated with self/shared-cancer TCRs or naive/un-activated status of CD8+ T cells." (PMID 37968259, 2023).
cancer (continued). "The top Cancer Hallmark pathways enriched in the SI rats, compared with the group-housed rats, included IFNα, IFNγ, and inflammatory responses, and IL6/JAK/STAT3 and TNFα signaling via NFκB." (PMID 36980301, 2023). "In the Cancer Hallmark pathway analysis, IFNα, IFNγ, inflammatory responses, and IL6/JAK/STAT3 signaling were suppressed significantly by JGT in tamoxifen-treated GH rats." (PMID 36980301, 2023). "In hallmark, the first-ranked interferon gamma response (covering 11 cancers) and the second-ranked inflammatory response (covering 9 cancers) were closely related to the immune response." (PMID 36945884, 2023). "In NSCLC and other cancers, increases in TNFɑ alone and TNFɑ, IFNγ, and IL2 together are associated with increased Th1 polarization post DC vaccination." (PMID 37830618, 2023). "We have previously shown that cancer-associated fibroblasts (CAFs), which are a dominant cell type in the stroma, can express PD-L1 following stimulation by interferon-gamma (IFN-γ) and that PD-L1-positive CAFs are present in NSCLC tissues." (PMID 37646826, 2023). "Generally, NEIL3 expression is closely associated with the C1 (wound healing) and C2 (IFNγ-dominant) immune subtypes in a majority of cancers." (PMID 36612106, 2022). "Expression of MLL3 or MLL4 is also negatively associated with GZMA, GZMB, and IFNG mRNA levels in a variety of human cancer types, highlighting increased immune cytotoxicity towards MLL3- and MLL4-low tumors." (PMID 36323669, 2022). "The low intensity stained LRPAP121–30-specific T cells also selectively recognized TAP-deficient cancer cells, but to much lower extent, considering the difference in IFNγ release." (PMID 34142235, 2022). "In the immune response caused by cancer or immunotherapy, interferon gamma (IFNγ) secreted by CD8+ T cells downregulates two subunits of System Xc−." (PMID 36581640, 2022). "This study demonstrated that a 4-gene IFNγ signature was associated with a favorable response to durvalumab treatment in both types of cancer." (PMID 35053427, 2022). "On the other hand, cancer cells can downregulate or mutate molecules involved in the IFNγ signaling cascade or harness the immunosuppressive functions of IFNγ to evade destructive immunity." (PMID 36142818, 2022). "Here, for the first time we applied a spheroid-based cancer model to characterize the antitumoral activity of virotherapy with Semliki Forest Virus vectors made to encode IFNg (SFV/IFNg)." (PMID 34835178, 2021). "IFNγ signaling inhibits angiogenesis and causes cancer cells to upregulate MHC class I receptors, making them more vulnerable to MHC-restricted killing." (PMID 34829860, 2021). "To perform a direct comparison between the repertoires and coverage of HLA-I and HLA-II in the context of these antigens and IFNγ treatment, we examined the 115 shared cancer associated antigens present in the HLA-I and HLA-II peptide datasets." (PMID 33968037, 2021). "Hypermethylation of the IFNγ promoter in CD8+ T cells isolated from cancer patients is associated with reduced IFNγ production following CD8+ T cell stimulation and with decreased T cell cytotoxicity." (PMID 33801234, 2021). "Tumors with upregulated ABAT transcript have enriched expression of genes in the gene ontology pathways of “mesenchymal-to-epithelial transition” and “interferon gamma signaling,” two pathways associated with limiting the spread of cancer." (PMID 33187258, 2020). "This permits quantification of cancer cell recognition with an enzyme-linked immune absorbent spot (ELIspot) assay directed against IFNγ." (PMID 32272797, 2020). "On the other hand, IFNγ is strongly associated with host protection against multiple types of cancers, in experimental models of cancer and in pre-clinical and clinical studies." (PMID 32722549, 2020).
cancer (continued). "The top six annotations of GSEA were associated with various cancer-related pathways, e.g., epithelial mesenchymal transition, interferon gamma response, interferon alpha response, cholesterol homeostasis, unfolded protein response, and angiogenesis." (PMID 33363203, 2020). "Next, functional characterization of these cell subsets showed reduced cytotoxicity and IFNγ production in Eomeslo ILC1s compared to Eomeshi cells, suggesting that lower Eomes levels are associated with poor cancer immunosurveillance by Group 1 ILCs." (PMID 32625207, 2020). "Genetic inactivation of IFNγ-signaling in cancer cells has been associated with failure of the immune system to clear cancer cells in murine models, and recently with ICI resistance, supporting its clinical relevance." (PMID 31735170, 2019). "Second, cancer cells can acquire mutations in the IFNγ signaling pathway that hinder their ability to respond to IFNγ, otherwise known as acquired resistance." (PMID 31133614, 2019). "In keeping with the effects of other reported somatic mutations associated with IFNγ resistance in cancer cells, we observed reduced PD-L1 upregulation after IFNγ stimulation in KD cells compared to Sc (p < 0.05)." (PMID 31552026, 2019). "Cancer is associated with the suppression of Th1 responses and, as a result, IFNγ is further aggravated by surgical stress." (PMID 29904108, 2018). "And in vitro truncating mutations of JAK1 and JAK2 results in insensitivity to IFNγ and its antiproliferative effects on cancer cells." (PMID 30294272, 2018). "Not surprisingly, loss of function mutations of MHC class I (e.g., loss of β2m) and key IFNγ signaling molecules JAK1/2 in the cancer are associated with intrinsic resistance to anti-PD-1 therapy." (PMID 30577797, 2018). "In a separate study, AR-depleted cancer associated fibroblasts (CAFs) promoted increased stem cell marker expression in human PCa cells, apparently via increased levels of Interferon gamma (IFN-γ) and macrophage colony-stimulating factor (M-CSF)." (PMID 29210989, 2017). "This is the first evidence showing that IFNγ inhibits CXCL8 secretion in a BRAF V600e mutated cancer cell line." (PMID 27555670, 2016). "The important role of immunosurveillance in cancer prevention has been demonstrated in immunodeficient mice such as IFNγ-deficient mice." (PMID 26040322, 2015). "Unexpectedly, IFNγ also appears in the 41-gene list whose overexpression is associated with cancer virulence." (PMID 26384298, 2015). "Taken together, effective cancer therapies tend to generate an acute-type inflammation, which is typically associated with increased levels of IL-1, IL-6, IL-17, IFNγ, IFNα/β, and several IFNγ-responsive chemokines." (PMID 22778760, 2012). "We previously found that pancreatic stellate cells (PSC), the main effector cells in cancer-associated fibrosis, are targets of IFNγ action in the pancreas." (PMID 21310022, 2011). "Three genes were associated primarily with progression to CIN3/cancer including IFNG, a cytokine that plays a role in innate immunity against viral or bacterial infections." (PMID 20084279, 2010). "Of the genes/regions associated with progression to CIN3/cancer, SNPs in IFNG (rs11177074) and between EVER2/TMC8 and EVER1/TMC6 (rs9893818) were statistically significant at p<0.05." (PMID 20084279, 2010). "The downregulation of NCR1 on NK cells, a phenotype prevalent in cancer, and its association with impaired cytotoxicity and increased IFNγ production, likely reflects a strategic adaptation to T. gondii infection, prioritizing tissue integrity and control of inflammation over cytotoxic actions." (PMID 40104068, 2025). "Since ICB therapies also enhance IFNγ expression, one of the underlying mechanisms may involve the IFNγ-induced IL-8 expression, resulting in increased cancer cell growth and resistance to ICB." (PMID 39123403, 2024).